DLEU1 (deleted in lymphocytic leukemia 1)
Diseases named in the same sentence as DLEU1 in open-access papers (continued):
Sharing a sentence is not in itself a finding about the gene and the disease.
cervical cancer (7 papers, 2018 to 2025). A primary or metastatic malignant neoplasm involving the cervix. "Accumulating evidence has demonstrated that the long non-coding RNA (lncRNA) lymphocytic leukaemia deletion gene 1 (DLEU1) is abnormally overexpressed in many cancer types, including cervical cancer (CC)." (PMID 39687982, 2025). "So far, lncRNA DDN-AS1, lncRNA TMPO-AS1, lncRNA RUSC1-AS1, and lncRNA DLEU1 have been detected to be upregulated in cervical cancer and acted as promoters in cervical carcinogenesis." (PMID 36561319, 2022). "In addition, overexpression of DLEU1 and RUSC1-AS1 was significantly associated with shorter overall survival of patients with cervical cancer." (PMID 36561319, 2022). "Overexpression of DLEU1 in cervical cancer cell lines promotes cell proliferation and invasion." (PMID 33324542, 2020). "Thus, DLEU1 facilitates EMT, resulting in progression and invasion of cervical cancer via the DLEU1–miR-381–HOX13 axis." (PMID 33324542, 2020). "Although growing evidence has demonstrated that the long non-coding RNA DLEU1 is involved in the progression of various cancers, its functional role and underlying mechanisms have not been explored in cervical cancer (CC)." (PMID 30581456, 2018). "Initially, we identified five necrosis-related lncRNAs, including lncRNA DDN-AS1, lncRNA DLEU1, lncRNA RGS5, lncRNA RUSC1-AS1, and lncRNA TMPO-AS1, for the construction of a signature that independently predict cervical cancer prognosis." (PMID 36561319, 2022).
endometrial cancer (6 papers, 2019 to 2023). Primary or metastatic malignant neoplasm involving the endometrium (mucous membrane that lines the endometrial cavity). "While in endometrial cancer, DLEU1 regulates SP1 expression via sponging miR-490 and aggravates the cancer development." (PMID 34113562, 2021). "Similarly, DLEU1 is found to stimulate endometrial cancer development." (PMID 34113562, 2021).
glioblastoma (6 papers, 2019 to 2024). The most malignant astrocytic tumor (WHO grade IV). "For instance, DLEU1 was upregulated in glioblastoma and downregulated expression of DLEU1 suppressed glioblastoma cell growth and enhanced cell apoptosis partly via regulating miR-4429." (PMID 35647200, 2022). "Nevertheless, the function and mechanism of DLEU1 in human glioblastoma multiforme (GBM) remain elusive and ill-defined." (PMID 31713587, 2019). "High expression level of DLEU1 was also observed in the three most acknowledged human glioblastoma cell lines U87 (P<0.05), U251 (P<0.01) and LN229 (P<0.01) in comparison with the normal brain glial cell line HEB, particularly in U251 and LN229 cells." (PMID 31713587, 2019). "Moreover, the TSP-4 secreted by CAF can improve the transcription level of HSF1 in glioblastoma cells and upregulate lncRNA DLEU1 to confer glioblastoma ferroptosis resistance." (PMID 37784082, 2023). "Increased expression levels of DLEU1 and TRAF4 in glioblastoma multiforme (GBM) tissues promote GBM cell proliferation and regulate cell migration through the Hippo signaling pathway and Wnt signaling pathway." (PMID 35242717, 2022).
oral squamous cell carcinoma (6 papers, 2018 to 2023). "We recently reported that one lncRNA, DLEU1, exerts oncogenic effects in oral squamous cell carcinoma through activation of IFITM1, one of the IRDS genes." (PMID 37443145, 2023). "We previously reported that DLEU1 (deleted in lymphocytic leukemia 1) is one of the lncRNAs overexpressed in oral squamous cell carcinoma (OSCC) cells, where it exhibits oncogenic activity." (PMID 34650128, 2021). "In oral squamous cell carcinoma (OSCC) cells, DLEU1 has oncogenic functionality and participates in migration, invasion, and xenograft formation." (PMID 32742772, 2020).
hepatocellular carcinoma (5 papers, 2019 to 2022). A malignant tumor that arises from hepatocytes. "However, the exact expression, biological function and underlying mechanism of DLEU1 in hepatocellular carcinoma (HCC) remain unclear." (PMID 31207081, 2019). "In cancer cells, DLEU1 (lncRNA deleted in lymphocytic leukemia 1) could serve as an oncogenic lncRNA that promotes hepatocellular carcinoma tumorigenesis by acting as a ceRNA to regulate the expression of IGF-1R and its downstream PI3K/AKT signaling pathway genes by directly sponging miR-133a." (PMID 33419093, 2021). "Also, IRAIN, Linc00319, and DLEU1 through negatively regulating IGF-1R could cause breast cancer, cervical cancer, and hepatocellular carcinoma." (PMID 33768092, 2021).
lymph node metastasis (4 papers, 2020 to 2026). "High DLEU1 expression correlated positively with lymph node metastasis and advanced clinical stages in PTC patients." (PMID 32910787, 2020). "Moreover, overexpression of DLEU1 was positively correlated with lymph node metastasis and advanced clinical stages." (PMID 35619131, 2022). "DLEU1 relative expression was significantly correlated with tumour size, cervical invasion depth, pathological grade, International Federation of Gynecology and Obstetrics (FIGO) stage and lymph node metastasis among patients with CC (p < .01 all)." (PMID 39687982, 2025).
osteosarcoma (4 papers, 2020 to 2022). A usually aggressive malignant bone-forming mesenchymal neoplasm, predominantly affecting adolescents and young adults. "Moreover, DLEU1 regulated osteosarcoma cell migration, invasion, and migration through targeting miR-671-5p." (PMID 35647200, 2022). "Furthermore, DLEU1 regulated osteosarcoma cell migration, invasion, and migration through targeting miR-671-5p." (PMID 35647200, 2022). "DLEU1 downregulation decreased osteosarcoma cell migration, invasion, and migration." (PMID 35647200, 2022). "Emerging research has reported that lncRNA DLEU1 performed an indispensable role in the genesis and progression of various tumors such as gastric cancer, osteosarcoma, pancreatic ductal adenocarcinoma, non-small cell lung cancer, and breast cancer, as well as resistance to chemotherapy in tumors." (PMID 33362537, 2020).
leukemia (3 papers, 2018 to 2024). A malignant (clonal) hematologic disorder, involving hematopoietic stem cells and characterized by the presence of primitive or atypical myeloid or lymphoid cells in the bone marrow and the blood. "DLEU1 is linked to demethylation in leukemia, and LINC00857 is correlated to demethylation in NSCLC." (PMID 35571069, 2022). "The gene DLEU1 regulates the NF-kB signaling pathway, inducing or inhibiting its activity, and the activation of NF-kB had previously been shown to promote leukemia cell survival, suggesting that DLEU1 can influence leukemogenesis." (PMID 39758420, 2024).
pancreatic ductal adenocarcinoma (3 papers, 2020 to 2022). An infiltrating adenocarcinoma that arises from the epithelial cells of the pancreas. "For examples, DLEU1 accelerates the development of pancreatic ductal adenocarcinoma carcinogenesis through the miR-381/CXCR4 axis." (PMID 34113562, 2021).
cholangiocarcinoma (2 papers, 2022 to 2025). A carcinoma that arises from the intrahepatic biliary tree (intrahepatic cholangiocarcinoma) or from the junction, or adjacent to the junction, of the right and left hepatic ducts (hilar cholangiocarcinoma). "The present research first demonstrated that DLEU1 was significantly increased and related to awful prognosis in cholangiocarcinoma." (PMID 35864972, 2022). "Nevertheless, the role of DLEU1 in cholangiocarcinoma progression remains obscure." (PMID 35864972, 2022). "Deletion in lymphocytic leukemia 1 (DLEU1) enhances cancer stemness by upgrading upregulating stem cell markers (SOX2, OCT4, NANOG, and KLF4) in cholangiocarcinoma." (PMID 40867514, 2025).
papillary thyroid carcinoma (2 papers, 2020 to 2022). "DLEU1 can also promote papillary thyroid carcinoma progression by sponging miR-421 and thus increasing ROCK1 expression." (PMID 35619131, 2022). "We investigated the role of long non-coding RNA DLEU1 (deleted in lymphocytic leukemia 1) in the progression of papillary thyroid carcinoma (PTC)." (PMID 32910787, 2020).
renal cell carcinoma (2 papers, 2020 to 2022). "Concordantly with our results, knockdown of lncRNA DLEU1 suppressed the proliferation by downregulating AKT signal pathway in renal cell carcinoma." (PMID 33362537, 2020).
cervical intraepithelial neoplasia (1 paper, 2025). "Our research showed that DLEU1 expression in the serum exosomes of patients with CC was significantly upregulated compared to that in patients with cervical intraepithelial neoplasia (CIN) and healthy controls (HCs) (both p < .001)." (PMID 39687982, 2025).
esophageal squamous cell carcinoma (1 paper, 2022). Esophageal squamous cell carcinoma (ESCC) is a type of esophageal carcinoma (EC) that can affect any part of the esophagus, but is usually located in the upper or middle third. "However, the biological functions and underlying mechanisms of DLEU1 in esophageal squamous cell carcinoma (ESCC) remain unclear." (PMID 35619131, 2022).
gastric adenocarcinoma (1 paper, 2021). "The results suggested that TMEM105, PVT1, FLJ22447, DLEU1, and LOC646588 closely related to the prognoses of patients with gastric adenocarcinoma." (PMID 34790582, 2021).
gynecological cancers (1 paper, 2020). "These are MEG3 (maternally expressed gene 3) and DLEU1 (deleted in lymphocytic leukemia 1), which have been identified in all three gynecological cancers." (PMID 31947591, 2020).
head and neck squamous cell carcinoma (1 paper, 2020). A squamous cell carcinoma that arises from any of the following anatomic sites: lip and oral cavity, nasal cavity, paranasal sinuses, pharynx, larynx, and salivary glands. "Elevated DLEU1 expression contributes to OSCC progress and high DLEU1 expression has been associated with shorter overall survival of primary head and neck squamous cell carcinoma patients." (PMID 32742772, 2020).
ischemic stroke (1 paper, 2022). A stroke disorder caused by obstruction of blood flow to the brain, due to thrombotic (local blood clot formation) or embolic (due to a blood clot or other material traveling from another site) event. "DLEU1 can also be a biomarker of non-cancerous diseases, like ischemic stroke, due to its involvement in regulating multiple biological processes and pathways." (PMID 35692841, 2022).
liposarcoma (1 paper, 2024). A usually painless malignant tumor that arises from adipose tissue. "The use of sWGS can reveal that myxoid pleomorphic liposarcomas exhibit complex chromosomal alterations, particularly the loss of 13q14, which encompasses the RB1, RCTB2, DLEU1, and ITM2B genes." (PMID 39473659, 2024).
lung carcinoma (1 paper, 2021). "Of these, 57 (25%) underwent alternative polyadenylation in lung cancer, including DLEU1, LINC01138, and PVT1." (PMID 34556645, 2021).
mycosis fungoides (1 paper, 2017). Classical mycosis fungoides is the most common type of mycosis fungoides (MF), a form of cutaneous T-cell lymphoma, and is characterized by slow progression from patches to more infiltrated plaques and eventually to tumors. "In mycosis fungoides tumour samples, deletion of the tumour suppressor gene DLEU1 is one of the reasons for tumourigenesis." (PMID 28598010, 2017).
neuropathic pain (1 paper, 2020). Chronic pain caused by damage to nerve fibers. "Therefore, our study focused on the significant role of DLEU1 in neuropathic pain rat models." (PMID 33167866, 2020). "Downregulation of DLEU1 reduced inflammation of the spinal cord and alleviated hypersensitivity in neuropathic pain in CCI rats, which may provide evidence for therapy protocols of neuropathic pain." (PMID 33167866, 2020).
Pain (1 paper, 2020). An unpleasant sensory and emotional experience associated with actual or potential tissue damage, or described in terms of such damage. "Since DLEU1 was reported to serve as a competitive endogenous RNA (ceRNA) at the post-transcriptional level in various diseases, we aimed to explore whether DLEU1 can serve as a ceRNA in neuropathic pain." (PMID 33167866, 2020).
pancreatic cancer (1 paper, 2022). "In pancreatic cancer, the lncRNA DLEU1 is overexpressed and targets miR‐381 to upregulate the expression of CXCR‐4, thereby aggravating the progression of pancreatic cancer." (PMID 35014178, 2022).
psoriasis (1 paper, 2018). An autoimmune condition characterized by red, well-delineated plaques with silvery scales that are usually on the extensor surfaces and scalp. "In our PsV vs. control meta-analysis, we identified a new psoriasis susceptibility locus at 13q14.2 (rs9591325; p = 7 × 10−9 [Wald test]; odds ratio = 1.25), which is located inside an intron of DLEU1." (PMID 30301895, 2018).
ulcerative colitis (1 paper, 2024). An inflammatory bowel disease involving the mucosal surface of the large intestine and rectum. "ZNF91, VDR, DLEU1, SATB2-AS1, and TP53TG1 in ulcerative colitis are related to the regulation of PPAR, AMPK, and metabolic signaling pathways." (PMID 39791702, 2024).
tumor (36 papers, 2013 to 2026). "Clinically, elevated DLEU1 expression was significantly associated with increased tumor infiltration depth (P = 0.040)." (PMID 41484982, 2026). "Of which, lncRNA lymphocytic leukaemia deletion gene 1 (DLEU1), a recently discovered non-coding RNA, its expression in tumour tissue was associated with HPV infection status and served as a biomarker in HPV-infected CC." (PMID 39687982, 2025). "To explore the molecular mechanisms underlying the pro-tumor activities of DLEU1, we resorted to TCGA database to identify molecules whose expressions are correlated with DLEU1." (PMID 35853854, 2022). "The DLEU1 is an lncRNA associated with tumor cell aggressiveness and migration." (PMID 33183321, 2020). "However, increased DLEU1 was positively associated with vascular invasion and tumour‐node‐metastasis (TNM) stage in HCC patients." (PMID 31207081, 2019). "In this study, real‐time quantitative polymerase chain reaction (qRT‐PCR) in HCC tissues and cell lines revealed that DLEU1 expression was up‐regulated, and the increased DLEU1 was closely associated with advanced tumour‐node‐metastasis stage, vascular metastasis and poor overall survival." (PMID 31207081, 2019). "While DLEU7 is a protein-coding gene, DLEU1 was recently discovered to be part of a bigger gene, BCMS, that has a potential tumor-suppressing function." (PMID 36525587, 2023). "As a lncRNA, the mechanisms mediating the pro-tumor activities of DLEU1 have been revealed in different types of cancers." (PMID 35853854, 2022). "We found that the expression of DLEU1 was significantly upregulated in tumor tissues and correlated with poor prognosis in ESCC patients." (PMID 35619131, 2022). "By activating ERK and STAT3 signaling, CKAP2 essentially mediated the pro-tumor activities of DLEU1." (PMID 35853854, 2022). "When transplanted into nude mice, the tumor growth of cells with DLEU1 overexpression was significantly promoted compared with that of control cells." (PMID 35619131, 2022). "In EdU incorporation assays, silencing DLEU1 depressed tumor cell proliferation, while enhanced DLEU1 boosted cellular proliferation." (PMID 35864972, 2022). "To decipher the underlying mechanisms of dysregulated DLEU1 expression in ESCC, we explored tumor-intrinsic oncogenic events in the DLEU1 gene locus." (PMID 35619131, 2022). "Although recent studies revealed the elevated expression and tumor promoting functions of DLEU1 in various solid tumors, the present study is the first to show that DLEU1 exerts its effects, at least in part, through activation of ISGs." (PMID 34650128, 2021). "Studies recently showed that DLEU1 is upregulated in various types of cancer and contributes to tumor development and chemoresistance." (PMID 34650128, 2021). "The present study also suggested that the expression of PVT1 and DLEU1 in tumor tissues was notably higher than that in normal tissues." (PMID 34790582, 2021). "Because DLEU1 is located on chromosome 13q14.3, a region frequently deleted in hematopoietic malignancies, DLEU1 was initially identified as a candidate tumor suppressor gene." (PMID 34650128, 2021). "DLEU1 knockdown in TPC-1 cells decreased in vivo xenograft tumor size and weight compared to controls in nude mice." (PMID 32910787, 2020). "Herein, we first corroborated the tumor-facilitating role of DLEU1 depended on SP1 through sponging miR-4429." (PMID 31713587, 2019). "The nude mice xenograft assays further revealed that knockdown of DLEU1 suppressed tumour growth in vivo." (PMID 31207081, 2019). "To confirm the oncogenic functionality of DLEU1 in vivo, we performed mouse xenograft experiments, which showed that siRNA targeting DLEU1 significantly suppressed xenograft tumor formation by OSCC cells in nude mice." (PMID 30069008, 2018). "We also found that administration of siRNA targeting DLEU1 suppressed tumor formation by OSCC cells in vivo." (PMID 30069008, 2018).